RHOA (ras homolog family member A)
Diseases named in the same sentence as RHOA in open-access papers (continued):
Sharing a sentence is not in itself a finding about the gene and the disease.
cancer (continued). "This change may lead to the persistent activation of RhoA, thereby affecting the metastatic potential of cancer cells." (PMID 40181839, 2025). "Consequently, RHOA overexpression in hypoxic conditions has a protective mechanism that facilitates cancer progression." (PMID 40600795, 2025). "Immunostaining also indicated the strong nuclear localization of RhoA in several cancer cell lines." (PMID 40136653, 2025). "Having demonstrated that cyclinA2 and cyclinB1 regulate the motility of cancer cells, we next wanted to test whether these cyclins have conserved roles in regulation of cell migration, morphology, RhoA activity and membrane tension in a non-cancer cell line." (PMID 40518827, 2025). "Our findings challenge the traditional genetic/epigenetic dichotomy in cancer, explaining RHOA hyperactivity in mutation-negative tumors." (PMID 41291745, 2025). "Additionally, there was a high frequency of activation in Interferon and RHOA Signaling pathways, along with other cancer-related pathways." (PMID 38464090, 2024). "Additionally, previous studies have also found that c-Myc suppresses the activity of RhoA affecting Actin dynamics in cancer cells." (PMID 38509115, 2024). "Also, mutations in Ras homolog member A (RhoA), a small GTPase, induced an OXPHOS signature in cancer cells." (PMID 38897995, 2024). "Notably, one of the targets of miR-520f-3p, NEK9, is implicated in the phosphorylation of ARHGEF2, which, in turn, activates RhoA, promoting enhanced cell motility and facilitating both local and distant cancer cell spread." (PMID 39456519, 2024). "These intracellular bacteria may promote cancer cell metastasis through the suppression of RhoA and ROCK activation, and the inhibition of ROCK or antibiotic treatment negates the viability changes caused by bacterial invasion." (PMID 39717276, 2024). "Since the activation of RhoA is required for cancer cell migration and PLK1 enhances RhoA activity through the interaction with RhoGDI1, we investigated whether PLK1 could affect the migration and invasion of cancer cells." (PMID 38355643, 2024). "As epidermal growth factor receptor (EGFR), Vav1, RhoA, Rac1, and BPGAP1 are all associated with cancer metastasis, BPGAP1 could provide a crucial checkpoint for the EGFR-BPGAP1-Vav1-Rac1-RhoA signaling axis for cancer intervention." (PMID 36598812, 2023). "Moreover, RhoA/Rock signaling pathway is crucial in the regulation of cancer cell motility by regulating cell cytoskeletal." (PMID 36899050, 2023). "For example, RhoA/ROCK and JUNB signaling pathways or SOX4 overexpression, which control NFIX expression both during embryonic development and in the context of cancer, have been linked to oxidative stress." (PMID 36901722, 2023). "However, the deregulated expression or activity of Rho family including RhoA appears to mediate key function in cancer." (PMID 37193711, 2023). "GEF-H1 is a major activating regulator of RhoA and an attractive target in cancer treatment." (PMID 37193711, 2023). "RhoA is upregulated in various human cancers such as ovarian, gastric, and testicular cancers." (PMID 37298689, 2023). "Furthermore, RhoA inactivating regulator, i.e., Rho GTPase activating protein 29 (ARHGAP29), has been shown to regulate cancer cell metastasis via RhoA/LIMK/CFL-1 signal." (PMID 37193711, 2023). "qRT-PCR results showed that ARAP1 OE did not cause similar effects on RhoA/B/C mRNA expression in different LUAD cancer cells." (PMID 38008882, 2023). "Furthermore, ROS promote the epithelial-to-mesenchymal (EMT) transition of cancer cells through cytoskeleton rearrangement induced by Rac1 (Rac family small GTPase 1), RhoA (Ras homolog family member A) and FAK (focal adhesion kinase)." (PMID 37760037, 2023). "Most of the work on transcriptional regulation of RhoA has been done in cancer models." (PMID 35563826, 2022).
cancer (continued). "What exactly triggers RhoA activation in response to the PM disruption caused by FSS has yet to be determined, but the fact that extracellular Ca2+ is essential for FSS resistance in cancer cells, suggests that Ca2+ influx could activate RhoA directly." (PMID 35103909, 2022). "As attested by the study, ARHGEF2 plays a key role in a variety of cancers by activating the RhoA signaling pathway, which may contribute to the proliferation and metastasis of cancer cells." (PMID 35896520, 2022). "Thus, we identify pre-existing and adaptive features of metastatic and drug-resistant cancer cells, which are enhanced by RhoA/SRF signaling and the brain TME during the evolution of osimertinib-resistant disease." (PMID 36509758, 2022). "Indeed, the MAPK/ERK pathway increases caveolin-1 expression in cancer cells and, through the induction of RhoA/Rho-associated protein kinase 1 (ROCK1), promotes cell contraction and favors cancer cell migration along the pre-existing collagen matrix." (PMID 36497384, 2022). "Platelets suppress apoptosis via enhancing Ras homolog family member A (RhoA)-myosin phosphatase target subunit 1 (MYPT1)- protein phosphatase 1 (PP1)-mediated yes-associated protein (YAP1) dephosphorylation and MAPK signaling in cancer cells." (PMID 35682700, 2022). "RhoA and Ras are two important members of Ras superfamily that regulates many aspects of cancer cell biology including cell division, proliferation and migration, whose inhibitors hold promising activity against cancer." (PMID 35186766, 2022). "Overexpression of RhoA gene and protein is found in various metastatic human cancers." (PMID 36180910, 2022). "For vinorelbine, EPHA2 codes for EPH receptor A2, a tyrosine kinase involved in cancer-related signaling, while NGEF codes for a guanine nucleotide exchange factor associated with signaling from EPH receptor A2, RhoA, Rac1 and CDC42 as well as cellular transformation and tumorigenesis." (PMID 36139690, 2022). "Finally, cancer-associated fibroblasts (CAFs) release exosomes highly enriched in ADAM10, thus increasing GTPase RHOA and enhancing cancer cell motility." (PMID 36139610, 2022). "The synergistic effect of Myc and RhoA-SRF pathway has a synthetic lethal effect, which is caused by the insufficient utilization of glutamine, suggesting that Myc and RhoA-SRF have metabolic coordination in maintaining the vitality of cancer cells." (PMID 35022030, 2022). "The involvement of RhoA in oncogenesis may be in part due to its ability to restructure the actin cytoskeleton and drive motility, as oncogene-mediated RhoA activation induces cancer cell migration and invasion." (PMID 35119068, 2022). "Conversely, CB1 receptors also inhibit carcinoma cell migration by reducing RhoA activity, indicating that the differential CB1 receptor-modulation of RhoA signaling may depend on factors such as the cell type and the pathophysiological context." (PMID 35798697, 2022). "In our data, GLRX was considered to regulate the cancer stem cell phenotype via non-canonical Wnt signaling pathways associated with RhoA and ABCG2 via Wnt5a and Wnt7b." (PMID 34794402, 2021). "The co-transcription of the RhoA/ROCK complex was reported in human cancers." (PMID 33407452, 2021). "However, the microfilament regulatory protein MENA accelerates RhoA activity and living cancer metastasis." (PMID 33816252, 2021). "Previous reports have demonstrated that loss of the ARHGAP42 BAR inhibitory domain is associated with decreased RhoA activity and increased cellular motility in vitro, and increased expression of ARHGAP42 in cancer cells is associated with increased cell migration and invasion." (PMID 34232960, 2021).
cancer (continued). "Additionally, in endometrial cancers, TRPV4 regulates cancer cell invasion through RhoA/ROCK1-dependent cytoskeletal changes and in glioma cancer cells TRPV4 promotes invasion through Akt/Rac1 signaling pathway." (PMID 34356643, 2021). "Having previously shown that RASSF1C/RhoA drive invasive behavior through the release of EVs, we next wanted to assess whether the cancer stem cell pool of RASSF1C cells promotes invasive behavior via EVs." (PMID 34532864, 2021). "Although our results indicate that RSV separately regulates RhoA-dependent cytoskeletal remodeling and TGFβ-dependent EMT to inhibit A549 cell migration, many reports have shown RhoA pathway is functionally linked to EMT in a variety of cancer cell lines." (PMID 33867987, 2021). "As a member of the Rho family, RhoA plays an important role in cancer cell metastasis." (PMID 33858415, 2021). "RhoA is a member of the Rho family of GTPase and has a dual role in cancer cells invasion." (PMID 34465801, 2021). "While analyzing multiple cancer disorders, we found highly variable expression among genes implicated in cancer: EEF1A1, GNAS, NPM1, PIM1, and RHOA are known oncogenes; H3F3A, PTPRC, SMARCB1, and B2M are possible oncogenes; and CASP8, JAK1, and PRKAR1A are known tumor suppressor genes." (PMID 34174938, 2021). "It is possible that the functions of RhoA in cancer are cell-context dependent." (PMID 34465801, 2021). "RhoA is critical for the migration, invasion and metastasis of various cancers, including RCC." (PMID 34208068, 2021). "RhoA is a key regulator of cancer cell proliferation, progression, and metastasis." (PMID 32089990, 2020). "RhoA could promote focal adhesion and regulates some cancer cell contractility, leading to cell migration, but blocking RhoA activity of RhoA could significantly inhibition the migration in wnt5a-induced cells." (PMID 32192495, 2020). "RhoA overexpression was associated with significantly impaired disease-free survival and distant metastasis-free survival (P = 0.045 and P = 0.041, respectively) in stage III cancer patients." (PMID 31976530, 2020). "Since BNIP-2 knockdown suppresses RhoA activity, we hypothesized that BNIP-2 knockdown could lead to increased motility of cancer cells through regulation of RhoA activity." (PMID 32789168, 2020). "Similarly, the effect of anti-cancer phytochemical rocaglamide-A inhibited the activity of RhoA, Rac1, and Cdc42 GTPases and suppressed metastasis formation." (PMID 32443784, 2020). "PKC-ζ has been shown to be involved in tumorigenesis, tissue invasion, and cancer progression through the modulation of cell migration machinery, such as Ras Homolog Family Member A (RhoA), Rac Family Small GTPase 1 (Rac1), and Epithelial Cell Transforming 2 (Ect2)." (PMID 32175276, 2020). "This acetylation of K7 may be extended for all fusion proteins containing RAB22A1-38 in cancers, and may affect their functions, such as binding to SmgGDS607, activation of RhoA, promotion of migration, invasion and metastasis." (PMID 32685017, 2020). "Although the mechanism of this mutation on tumorigenesis is unclear, since RhoA signaling is inversely correlated with Rac1 in some cancers, one possibility is that reduced RhoA activity may promote tumorigenesis through enhanced Rac1 signaling." (PMID 32392742, 2020). "SMURF1‐mediated RhoA degradation is vital for cancer cell metastasis." (PMID 33377649, 2020). "Directional cell migration, an important step of cancer invasion and metastasis, requires dynamic changes of the cytoskeleton and cell-matrix adhesions, which are tightly regulated by Rho guanosine triphosphatases (GTPases; e.g., RhoA, Rac1, and Cdc42)." (PMID 32789168, 2020). "This may be due to the fact that coordinated events between Rac1 and RhoA are necessary for effective migration in cancer metastasis." (PMID 32722576, 2020).
cancer (continued). "Scaffold proteins fine-tune RhoA activity on the basis of their concentration, which may result in different migratory behaviors between normal cells and cancer cells." (PMID 32789168, 2020). "Moreover, the derivative compound DC‐Rhoin04 inhibits the migration and invasion of cancer cells, through targeting this allosteric pocket of RhoA." (PMID 32714746, 2020). "Of the RhoA-positive stage III cancer patients, 11 (44%) of 25 patients experienced recurrence." (PMID 31976530, 2020). "In addition, some DGKs control cancer cell migration by regulating the activities of the Rho GTPases Rac1 and RhoA." (PMID 32722576, 2020). "Increased RhoA activity in diffuse gastric cancer has been hypothesized to promote cancer stem cell-like phenotypes and chemoresistance, and RhoA inhibition might reverse chemoresistance." (PMID 32150838, 2020). "Moreover, DC‐Rhoins inhibit the migration and invasion of cancer cells, through targeting Cys107 residue of RhoA in cells." (PMID 32714746, 2020). "RhoA and RhoC were frequently activated in many cancers and can stimulate malignant transformation." (PMID 31097692, 2019). "However this concept was extended and challenged by the direct observation of RhoA signalling at the leading edge of mouse fibroblasts and human cancer cells migrating in 2D cell culture." (PMID 30292078, 2019). "Intriguingly, RHOA, a small GTPase, whose activity is regulated by the mevalonate pathway, has been involved in the formation and shedding of plasma-membrane-derived EVs in cancer cells by activating a specific signaling." (PMID 31319863, 2019). "Mechanistically our study suggests that by increasing the expression of chemokine receptors, CXCR4 and CCR5, decreased RhoA expression increases the proclivity of cancer cells for the sentinel lymph node and enables the cancer cells to have access to the circulation and metastasize." (PMID 31705019, 2019). "Since RhoA is critical for multiple cellular functions such as cell motility and division, whether this regulation existed in cancer would be highly informative in understanding the significance of cytoskeleton and signal transduction in human disease." (PMID 31623230, 2019). "Upon the activation of Rac1 and RhoA, cancer cells migration are enlarged." (PMID 31870092, 2019). "Although there is no CHS-111 preclinical study, it might be useful in the treatment of RhoA overexpressing cancers." (PMID 30884855, 2019). "Instead of acting solely as a cancer indicator, RhoA also acts as a functional regulator." (PMID 31339860, 2019). "Therefore, RhoA is a crucial regulator of cancer progression for its contribution to actin cytoskeletal reorganization that drives cell motility and invasion." (PMID 30678736, 2019). "Cross-talk between the hypoxia/HIF-1α and Rho pathways has already been investigated in different cell models, such as cancer cells, fibroblasts, endothelial cells, and MSCs; however, the effects of hypoxia on RhoA levels and activation show many differences among cell types." (PMID 30925808, 2019). "In addition to their fundamental functions, Rho GTPases such as RhoA and RhoB play a significant role in cancer progression and inflammation." (PMID 31331053, 2019). "Among the various effectors, mDia and ROCK are two best-described effectors that are important for RhoA-mediated regulation of cancer cell invasion/metastasis by stabilizing adherens junctions, regulating myosin light chain 2 (MLC2) phosphorylation and focal adhesion dynamics." (PMID 31705019, 2019). "Thus, sumoylation of RhoGDI1 negatively regulates the activity of RhoA and Rac1, leading to a decrease in cancer cell migration." (PMID 31492019, 2019). "Moreover, the expression of the migration-related proteins FAK, RhoA and Fascin-1 was also increased, suggesting that mature adipocytes can also contribute to modulating cancer cell progression by reprogramming cancer cells signaling." (PMID 31817072, 2019).
cancer (continued). "Thus, molecular and biochemical studies of RHOA, as related to other cancer hallmarks, need to be performed in the future." (PMID 31156701, 2019). "Instead the crosstalk between MDA-MB-231 cells and CAFs leads to increased migration, which depends on the activation of RhoA/ROCK/MLC signaling in cancer cells via two distinct mechanisms, the secretion of IGF-1 by CAFs and the upregulation of PAI-1 in cancer cells." (PMID 29535813, 2018). "Previous studies show that ERG regulates the expression of frizzled class receptor 4, E-cadherin, vimentin, ras homolog family member A, vascular endothelial growth factor receptor 2, and zinc finger E-box binding homeobox 1/2 during cancer metastasis and epithelial–mesenchymal transition process." (PMID 29773901, 2018). "However, many cancers and some somatic cells (e.g. myoblasts and satellite cells) can also enter an amoeboid migration mode that is dependent on RhoA-ROCK signaling and weaker adhesion, but lacks dependence on extracellular proteolysis." (PMID 29743635, 2018). "In support our data, a recent study reported that several cancer types are associated with increased expression and activity of the ECT2 RhoGEF and decreased expression and activity of the DLC1 RhoGAP, leading to increased RhoA activity." (PMID 30278072, 2018). "To determine whether IGF-1 promotes cancer cell invasion via the RhoA/ROCK pathway, we examined the effect of recombinant IGF-1 on RhoA-GTP expression." (PMID 29535813, 2018). "RXRA, CDKN1A, and RHOA are the members of pathways in cancer." (PMID 29738475, 2018). "Also, CAFs were found to secrete ADAM10-rich exosomes to promote cell motility and activate RhoA and Notch signaling in several cancer cell lines." (PMID 30227608, 2018). "Moreover, excessive expression of RhoA and RhoC are found to be more than 30% of all cancers which make them a vulnerable molecular target for cancer therapy." (PMID 29861465, 2018). "More recently, identification of point mutants in the Rho GTPases Rac1, RhoA, and Cdc42 in human tumors has finally given rise to a new paradigm, and we can now state with confidence that Rho GTPases serve as oncogenes in several human cancers." (PMID 30544828, 2018). "We do not understand how dominant-negative mutants of RhoA can cause cancers, and we do not understand why Rac1/P29S can be an oncogene when it negatively regulates adhesion-dependent cell migration and invadopodia formation." (PMID 30544828, 2018). "Moreover, it has been shown that the activation of IL‐8 signalling pathways leads to RhoA activation and actin stress fibre formation in cancer and endothelial cells." (PMID 29517849, 2018). "Therefore, we examined CDC42, RAC1, and RHOA as potential target proteins of F806 based on their role in the formation and turnover of actin filaments, as well as cancer invasion and metastasis." (PMID 30327774, 2018). "Notably, the RhoGAP DLC1, a tumor suppressor protein inactivating RhoA in many types of cancer, is phosphorylated by PKC/PKD protein kinases on Ser residues, which create binding sites for 14-3-3 proteins." (PMID 29545927, 2018). "In that paper, the authors found that CD151 could regulate RhoA activation and the dynamic stability of carcinoma cell-cell contacts." (PMID 29568359, 2018). "Moreover, RhoA GTPase is crucial in cancer metastasis, and Skp2 induces RhoA transcription and consequently promotes cell migration, invasion, and cancer metastasis." (PMID 28157698, 2017). "Recently it has been reported in cancer cells and fibroblasts that vimentin depletion induced phosphorylation of the microtubule-associated GEF-H1, and thereby increased RhoA activity, myosin light chain phosphorylation, actin stress fiber assembly and cell contractility." (PMID 28912461, 2017).